ACTR3 (actin related protein 3)
Description:
ATP-binding component of the Arp2/3 complex, a multiprotein complex that mediates actin polymerization upon stimulation by nucleation-promoting factor (NPF). The Arp2/3 complex mediates the formation of branched actin networks in the cytoplasm, providing the force for cell motility. Seems to contact the pointed end of the daughter actin filament. In podocytes, required for the formation of lamellipodia downstream of AVIL and PLCE1 regulation. In addition to its role in the cytoplasmic cytoskeleton, the Arp2/3 complex also promotes actin polymerization in the nucleus, thereby regulating gene transcription and repair of damaged DNA. The Arp2/3 complex promotes homologous recombination (HR) repair in response to DNA damage by promoting nuclear actin polymerization, leading to drive motility of double-strand breaks (DSBs). Plays a role in ciliogenesis.
Synonyms: ARP3
Tractability: Small molecule: a structure with a bound ligand is known; a high-quality ligand is known. PROTAC: ubiquitination databases record sites on it; its protein half-life has been measured; a small molecule that binds it is known.
Gene: Protein-coding gene on chromosome 2 (113,889,600 to 113,962,596, forward strand). Ensembl gene ENSG00000115091.
Subcellular location: Cytoplasm, cytoskeleton; Cell projection; Nucleus
Pathways (Reactome):
Developmental Biology: EPHB-mediated forward signaling
Disease: FCGR3A-mediated phagocytosis
Immune System: Regulation of actin dynamics for phagocytic cup formation
Signal Transduction: RHO GTPases Activate WASPs and WAVEs
Vesicle-mediated transport: Clathrin-mediated endocytosis
Gene Ontology:
Molecular function: actin filament binding; protein binding; structural constituent of cytoskeleton
Biological process: Arp2/3 complex-mediated actin nucleation; cilium assembly; positive regulation of lamellipodium assembly; positive regulation of transcription by RNA polymerase II; actin polymerization-dependent cell motility
Cellular component: Arp2/3 protein complex; cytoplasm; extracellular exosome; focal adhesion; lamellipodium; membrane; nucleus; actin cytoskeleton; cytosol; site of double-strand break; brush border; cell-cell junction; cytoskeleton
Genetic constraint (gnomAD): Loss-of-function variants: 9 observed, 34.1 expected, observed/expected ratio (o/e) 0.26, 90% interval 0.16 to 0.46. The upper end of that interval is the gene's LOEUF score, 0.46, which puts it in group 2 of 6, group 1 being the genes least tolerant of losing a copy. Missense variants: 206 observed, 369.77 expected, observed/expected ratio (o/e) 0.56, 90% interval 0.5 to 0.62. Synonymous variants: 126 observed, 122.86 expected, observed/expected ratio (o/e) 1.03, 90% interval 0.89 to 1.19.
Homologues: Orthologues: macaque ACTR3 (100% identical), mouse Actr3 (99% identical), rat Actr3 (99% identical), guinea pig ACTR3 (96% identical), tropical clawed frog actr3 (95% identical), dog ACTR3 (94% identical), pig ACTR3 (86% identical), Drosophila melanogaster Arp3 (81% identical), Caenorhabditis elegans arx-1 (77% identical). Paralogues in human: ACTR3B (90% identical), ACTR3C (42% identical), ACTB (38% identical), ACTA1 (38% identical), ACTA2 (38% identical), ACTC1 (38% identical), ACTG1 (38% identical), ACTG2 (38% identical), ACTBL2 (37% identical), ACTR1A (36% identical), ACTR1B (35% identical), ACTR2 (33% identical), and 14 more.
Diseases named in the same sentence as ACTR3 in open-access papers:
ACTR3 is named in the same sentence as 41 diseases in open-access papers, as found by Europe PMC text mining. Sharing a sentence is not in itself a finding about the gene and the disease. The quoted sentences say what the papers report.
hepatocellular carcinoma (3 papers, 2021 to 2025). A malignant tumor that arises from hepatocytes. "As compared with the less studied ACTR3, the potential of ARPC5 as a prognostic biomarker has been investigated in multiple cancer types such as hepatocellular carcinoma and multiple myeloma." (PMID 34868230, 2021).
lung cancer (3 papers, 2020 to 2021). A malignant neoplasm involving the lung. "It is worth noting that in this study, 8 (ACTR3, ARF4, PGRMC1, RPS23, WDR12, ACTR2, SIAH1, and RPS27L) of 12 hub genes are related to cancers, such as lung cancer, epithelial ovarian cancer, gastric cancer, glioblastoma, breast cancer, and esophageal cancer." (PMID 33391181, 2020). "Candidate genes ACTR3, ARPC5, and HNRNPK were highly expressed in almost all types of lung cancer immune cells, while RAB13, PA2G4, and WDR12 were found to be less abundant in the majority of myeloid populations in lung cancer." (PMID 34868230, 2021).
breast carcinoma (2 papers, 2020 to 2023). "The high expression of disulfidptosis genes (e.g., SLC3A2, RPN1, BRK1, ACTR2, ACTR3, SLC7A11, and NCKAP1) in the KM analysis of breast cancer indicated the poor prognosis of patients." (PMID 38035071, 2023).
colorectal cancer (2 papers, 2017 to 2024). A primary or metastatic malignant neoplasm that affects the colon or rectum. "NUMA1 is related to poor prognosis in esophageal squamous cell carcinoma and ACTR3 is described as associated with colorectal cancer lymph node metastasis." (PMID 40603632, 2024).
Salmonella Infections (2 papers, 2019 to 2023). Infections with bacteria of the genus SALMONELLA. "The role of the Arp2/3 complex in Salmonella infections has been somewhat conflicting (17, –, 19), but here we demonstrated that mutants with clonal mutations generated in the ACTR3 and ARPC4 genes showed strong resistance to S. Typhimurium infections." (PMID 31594818, 2019).
cervical adenocarcinoma (1 paper, 2025). An adenocarcinoma arising from the cervical epithelium. "Noteworthy is the observation that ACTR3 expression in cervical squamous carcinoma was significantly greater compared to that in cervical adenocarcinoma." (PMID 41366959, 2025). "The findings from the immunohistochemical assessment indicated that, in contrast to normal cervical tissue, there was a marked increase in the expression levels of ACTR3 (P < .001), KI67 (P < .001), and CK7 (P < .001) in cervical adenocarcinoma." (PMID 41366959, 2025).
cervical cancer (1 paper, 2025). A primary or metastatic malignant neoplasm involving the cervix. "The identification of ACTR3 as a potential biomarker not only enhances our understanding of cervical cancer biology but also opens new avenues for targeted therapies and immunotherapeutic interventions." (PMID 41366959, 2025). "ACTR3 expression in cervical cancer specimens was evaluated by immunohistochemistry." (PMID 41366959, 2025). "However, the role of ACTR3 in cervical cancer remains unclear." (PMID 41366959, 2025).
cervical squamous cell carcinoma (1 paper, 2025). A squamous cell carcinoma arising from the cervical epithelium. "In summary, this study highlights the critical role of ACTR3 and its associated genes in the prognosis of cervical squamous cell carcinoma, underscoring the potential of ACTR3 as a valuable biomarker." (PMID 41366959, 2025). "Furthermore, a similar trend was observed in cervical squamous cell carcinoma, where the expression levels of ACTR3 (P < .001), KI67 (P < .001), and CK7 (P < .001) were also significantly elevated when compared to normal cervical tissue." (PMID 41366959, 2025).
iron deficiency (1 paper, 2012). "For example, actin-related protein 3 and tubulin α-1 chain were key gatekeeper proteins associated with cytoskeletal functions, whereas ADP-ribosylation factor-like 3, dihydropyrimidinase-related protein 2 and chaperonin containing TCP1 were identified in this role with iron deficiency." (PMID 23110188, 2012).
mastitis (1 paper, 2023). Inflammation of breast tissue during lactation or postpartum due to an obstructed duct or infection. "In this study, the ZRANB3, PIAS1, ACTR3, LPCAT2, MGAT5, and SLC37A2 genes in Xinjiang brown cattle, which are associated with mastitis resistance, were identified using a GWAS." (PMID 37372369, 2023). "These six genes (ZRANB3, PIAS1, ACTR3, LPCAT2, MGAT5, and SLC37A2) are all potentially associated with mastitis resistance." (PMID 37372369, 2023).
Obesity (1 paper, 2025). Accumulation of substantial excess body fat. "Zn-alpha-2 glycoprotein, immunoglobulin chains, and actin-related protein-3, which are high in people with obesity, decreased 1 month after bariatric surgery." (PMID 40565086, 2025).
opisthorchiasis (1 paper, 2017). Infection with flukes of the genus Opisthorchis. "ESP-induced early changes in host cells highlighted by proteomics were also confirmed for Opisthorchis viverrini, and indeed, plasma actin-related protein 3 (ARP3) autoantibody and 14-3-3 eta protein were identified as putative new diagnostic markers of opisthorchiasis." (PMID 29095820, 2017).
oral cancer (1 paper, 2020). "The last two hub genes with low expression in oral cancer were including ACTR3 and MYH11." (PMID 32597160, 2020).
Proteinuria (1 paper, 2024). Increased levels of protein in the urine. "Proteinuria and GSFS are caused by a point mutation in ACTR3 at BUF/Mna in rats." (PMID 38891801, 2024).
cancer (10 papers, 2014 to 2025). A tumor composed of atypical neoplastic, often pleomorphic cells that invade other tissues. "Elevated expression levels of ACTR3 have been consistently associated with poor overall survival across various cancer types, including CESC." (PMID 41366959, 2025). "ACTR3 is a gene closely related to the occurrence and development of cancer, showing important biological roles in various tumor types." (PMID 41366959, 2025). "Higher expression of these subunits correlates significantly with poor patient survival and advanced cancer stages, with ACTR3, ARPC2, and ARPC5 showing positive correlations with immune cell infiltration." (PMID 41332982, 2025). "A univariate Cox regression analysis was conducted to evaluate the relationship between ACTR3 expression levels and OS across these cancer types." (PMID 41366959, 2025). "Particularly, the cell cycle and mitotic regulatory genes expression including: CDK2, CDK2AP2, ACTR3, and chromosome structure associated genes like SMC4, INCENP and GNL3L are changed in treated cancer cells." (PMID 30202240, 2018). "ACTR3, also known as ARP3, encodes a protein involved in actin polymerization, essential to cell motility and metastasis of cancer cells." (PMID 30323283, 2018). "The correlation of ACTR3 with immune cell infiltration further emphasizes its role in the tumor microenvironment, potentially influencing immune evasion mechanisms that are critical for cancer progression." (PMID 41366959, 2025). "In order to explore the possible differences and outcomes linked to ACTR3 expression between malignant tissues and their adjacent normal tissues, we performed an analysis utilizing data from 33 different cancer types obtained from TCGA and the GTEx project." (PMID 41366959, 2025). "The GSEA results indicated that ACTR3, ARPC2, and ARPC5 are involved in multiple cancer-related pathways that promote the development of HCC." (PMID 34307456, 2021).
tumor (8 papers, 2008 to 2025). "The association of ACTR3 with neuroactive ligand-receptor interactions and calcium signaling pathways underscores its potential role in modulating tumor microenvironment interactions and cellular signaling dynamics." (PMID 41366959, 2025). "In addition, the high expression of ACTR3 is also associated with the maintenance of the immunosuppressive state in the tumor microenvironment, which may be achieved by reducing the levels of interferon-γ and inhibiting the function of effector T cells." (PMID 41366959, 2025). "This study aimed to determine if ACTR3 overexpression affects CC survival and explore its impact on the tumor immune microenvironment." (PMID 41366959, 2025). "A similar trend was observed for anti-TOP2A and anti-ACTR3 antibodies, which showed a significant decrease in positivity from early to late tumor stages (43-50% vs. 22-24%)." (PMID 40990023, 2025). "Future studies should focus on validating these findings in larger cohorts and exploring the mechanistic underpinnings of ACTR3’s role in tumor progression and immune modulation." (PMID 41366959, 2025). "The results showed that the expression of ARPC2 was negatively correlated with tumor purity (Rho = -0.169, p = 1.6e-03), whereas the expression of ACTR3 and APRC5 was irrelevant to tumor purity." (PMID 34307456, 2021). "We further investigated the effect of high expression of IL-35-related FXR1 and ACTR3 on tumor microenvironment (TME) and found that ACTR3 was significantly associated with EMT signatures and FXR1 was positively associated with NSCLC signatures, which were significantly and positively correlated." (PMID 40259042, 2025). "Coupled with the visualization of ACTR3 expression patterns, we observed a notable decline in the overall expression levels of ACTR3 in tissue stem cells and smooth muscle cells within the tumor group." (PMID 41366959, 2025). "Moreover, the relationship between ACTR3 expression and immune cell infiltration presents an intriguing aspect of tumor biology." (PMID 41366959, 2025). "This suggests that high ACTR3 expression may contribute to an immunosuppressive tumor microenvironment, potentially facilitating tumor growth and metastasis." (PMID 41366959, 2025). "Further analysis shows that ACTR3 may promote tumor progression by regulating cell cycle-related pathways (such as CCNA2) and extracellular matrix receptors (such as ITGB1)." (PMID 41366959, 2025). "Research investigated ACTR3 expression levels related to PI3K/Akt/mTOR pathway and its influence on tumor immunology and clinical outcomes." (PMID 41366959, 2025). "Gene levels corresponding to invasion-related EV proteins showed that five genes (annexin A1, actin-related protein 3, integrin-β1, insulin-like growth factor 2 receptor and programmed cell death 6-interacting protein) were significantly higher in GBM tumours." (PMID 36071478, 2022). "This is supported by observations that tumours cells produce more exosomes per cell than normal cells and PDCD6IP and ACTR3 levels are higher in GBM tumours compared to normal tissue." (PMID 27770278, 2017).
infection (1 paper, 2023). The state of being infected such as from the introduction of a foreign agent such as serum, vaccine, antigenic substance or organism. "At 24 h of infection, CC of Arp2/3 protein complex involved in the BP of positive regulation of actin filament polymerization was significantly enriched, which was closely associated with the significant expression of Actr3 protein." (PMID 37587524, 2023).
ACTR3 also shares sentences with these, for which no sentence is quoted: active tuberculosis (2 papers); pancreatic cancer (2); acute myeloid leukemia (1); atherosclerosis (1); cholangiocarcinoma (1); chromophobe renal cell carcinoma (1); clear cell renal cell carcinoma (1); colon cancer (1); endometrial carcinoma (1); epithelial ovarian cancer (1); esophageal cancer (1); esophageal squamous cell carcinoma (1); gastric cancer (1); glioblastoma (1); head and neck squamous cell carcinoma (1); mesothelioma (1); multiple myeloma (1); neurological disease (1); non-small cell lung carcinoma (1); papillary renal cell carcinoma (1); Parkinson disease (1); periodontitis (1); renal cell carcinoma (1); skin cutaneous melanoma (1).